DISC1 (DISC1 scaffold protein)
Diseases named in the same sentence as DISC1 in open-access papers (continued):
Sharing a sentence is not in itself a finding about the gene and the disease.
glioblastoma (6 papers, 2016 to 2025). The most malignant astrocytic tumor (WHO grade IV). "DISC1 was reported to affect mitochondrial dynamics by upregulating Drp1 expression in glioblastoma cells." (PMID 31929114, 2020). "They observed greater expression of DISC1 in glioma cells than in normal cells, and found that DISC1 knockdown significantly inhibited glioblastoma cell proliferation, migration, invasion, and stem cell self-renewal." (PMID 31850367, 2019). "A relatively higher expression of DISC1 was observed on glioma cells, and knocking down of DISC1 by shRNA significantly inhibited glioblastoma cell proliferation, migration, invasion and stem cell self-renewal." (PMID 30233327, 2018). "Taken together, our findings reveal that DISC1 affects glioblastoma cell development via mitochondria dynamics partly by down regulation of Drp1." (PMID 27852062, 2016). "For the first time, our data show that DISC1 have an important role in glioblastoma cell proliferation, migration, invasion and cancer stem-like cell self-renewal by regulating mitochondrial dynamics via Drp1." (PMID 27852062, 2016). "In the present study, we found notable increase of DISC1 protein level in human glioblastoma cells and inhibition of DISC1 by shRNAs reduced glioblastoma cell proliferation, migration, invasion and stem cell self-renewal." (PMID 27852062, 2016). "All studies showed statistically significant up-regulation of DISC1 expression in glioblastoma compared to the normal tissues." (PMID 27852062, 2016). "We also proved this event in glioblastoma cells, that knockdown of DISC1 by shRNA produced ring or lariat-like mitochondria, indicating that DISC1 participated in mitochondrial fusion and/or fission." (PMID 27852062, 2016). "Moreover, in glioblastoma, knockdown of DISC1 was found to significantly inhibit cell proliferation, migration, and invasion in vitro and in vivo." (PMID 31850367, 2019). "Furthermore, Transwell migration assays revealed that knockdown of DISC1 significantly restrained glioblastoma cell invasion." (PMID 27852062, 2016). "We further investigated whether the reduction of DISC1 would affect the mitochondrial morphology of glioblastoma cells." (PMID 27852062, 2016). "The effect of DISC1 on glioblastoma cell self-renewal was further examined." (PMID 27852062, 2016). "Thus, knockdown of DISC1 significantly inhibited the proliferation of glioblastoma cells both in vitro and in vivo." (PMID 27852062, 2016). "Glioblastoma is one of the most lethal brain cancers, and DISC1 is found to be up-regulated in glioblastoma through systematic bioinformatic analyses, suggesting that DISC1 may play a role in GBM tumorigenesis." (PMID 27852062, 2016). "Furthermore, the higher expression of DISC1 was detected in glioblastoma tissues than normal tissues." (PMID 27852062, 2016). "In all, our data suggested that DISC1 could affect mitochondria dynamics of glioblastoma cell via promoting Drp1 expression." (PMID 27852062, 2016). "We also reported here that shRNA-mediated knockdown of DISC1 inhibited glioblastoma cell migration and invasion, indicating that mitochondrial dynamics had an important role in gliomblastoma migration and invasion, and DISC1 regulated the mitochondria dynamics in part by blocking Drp1." (PMID 27852062, 2016). "Furthermore, we characterized the molecular basis of DISC1 in glioblastoma carcinogenesis." (PMID 27852062, 2016). "Indeed, our results showed that reduced DISC1 by shRNA could suppress glioblastoma cell proliferation in vitro and in vivo, inhibit glioblastoma migration, invasion and glioblastoma stem-like cells self-renewal." (PMID 27852062, 2016). "In addition, down-regulation of DISC1 decreased cell migration and invasion of GBM and self renewal capacity of glioblastoma stem-like cells." (PMID 27852062, 2016).
glioblastoma (continued). "While the role of DISC1 in tumorigenesis has not been well studied to date, studies have demonstrated its ability to promote non-small cell lung cancer cell proliferation while inhibiting glioblastoma cell proliferation." (PMID 40424447, 2025).
mood disorder (6 papers, 2014 to 2021). A cognitive disorder a disturbance in which the person's mood is hypothesized to be the main underlying feature. "The major feature in mitophagy malfunction seems to be related to mutated DISC1, since it is involved in the impaired recognition of damaged mitochondria through all neuropsychiatric diseases with connections to mood disorders, suggesting that DISC1 might be a new relevant pharmacological target." (PMID 33918863, 2021). "Pathological isoforms of DISC1 lead to abnormal neuronal development and mood disorders." (PMID 34295268, 2021).
Asperger syndrome (5 papers, 2011 to 2017). "Up to know, besides two case reports, only one published research detected DISC1 was associated with autism and Asperger syndrome using family-based association analysis." (PMID 21569632, 2011). "In a previous study, a Finnish group reported a positive association of rs1322784 with Asperger syndrome besides a significant association of a DISC1 intragenic microsatellite with autism." (PMID 21569632, 2011). "In a previous study, a Finnish group demonstrated that DISC1 polymorphisms were associated with autism and Asperger syndrome." (PMID 21569632, 2011). "They established association between autism and a DISC1 intragenic microsatellite D1S2709 and found that one intragenic SNP, rs1322784, was associated with Asperger syndrome." (PMID 21569632, 2011).
memory impairment (5 papers, 2017 to 2025). "It is known that C57BL/6J mice carry an exonic deletion in Disc1, which produces a truncated DISC1 protein that mimics the putative phenotypic effects of the disease-associated chromosomal translocation, resulting in memory impairment and fewer synaptic spines." (PMID 28331639, 2017). "We propose that reduced spontaneous activity in the developing OB might contribute to altered maturation of the hippocampal–prefrontal network, leading to memory impairment in immune-challenged Disc1+/− mice." (PMID 40447445, 2025). "However, no negative symptoms (assessed by the social interaction test), motor deficit (travel distance in the open field test), or memory impairments (novel object recognition test) were detected in DISC1-Δ3 mice." (PMID 36131044, 2022). "For example, DISC1 (Disrupted in Schizophrenia) regulates dendritic spine morphology via Rac1 and mutations in the cofilin kinase PAK3 lead to X-linked mental retardation and memory impairments." (PMID 28912711, 2017).
neuroblastoma (5 papers, 2014 to 2021). Neuroblastoma (NB) is the most common solid, extracranial childhood tumor. "Similar results were observed in response to bradykinin, another stimulant that induces IP3-mediated ER calcium release in EXOC1- or DISC1-knockdown differentiated neuroblastoma CAD cells." (PMID 25732993, 2015). "In neuroblastoma cells, overexpressed DISC1 is able to recruit homologous soluble C-terminal DISC1 fragment and heterologous dysbindin-1 to aggresomes, leading to their co-precipitation to the ionic detergent-insoluble fraction." (PMID 27462430, 2015). "IP3R1 activities were significantly decreased in DISC1 knockdown cells and mouse neuroblastoma CAD (Cath.-a-differentiated) cells by specific shRNAs." (PMID 25732993, 2015). "Similarly, NLF neuroblastoma cells transfected with full length human DISC1 or mouse Disc1 were used to test the specificity of the VHH-Fc antibody." (PMID 29324815, 2018). "DISC1 protein forms aggresomes when overexpressed in neuroblastoma cells, COS cells and neurons." (PMID 27462430, 2015). "FLAG-TRAK1 also co-immunoprecipitates endogenous 100 kDa full-length DISC1 from the human embryonic kidney cell line HEK293, while endogenous TRAK1 co-immunoprecipitates endogenous 100 kDa DISC1 from HEK293 cells and the human neuroblastoma cell line SH-SY5Y." (PMID 24092329, 2014).
behavioral disorders (4 papers, 2017 to 2022). "This animal model was created to mimic DISC1 aggregates observed in a subset of patients with mental illness and thus to represent as an animal model for sporadic forms of DISC1 protein-linked behavioral disorders." (PMID 31057438, 2019). "The PDE4 isoform PDE4B1 also interacts with the DISC1 protein, implicated in neural development and behavioral disorders." (PMID 29197324, 2017). "Suppressing Wif1 in OPCs rescues synaptic loss and behavioral disorders in DISC1-Δ3 mice." (PMID 36131044, 2022).
Parkinson disease (4 papers, 2014 to 2021). A progressive degenerative disorder of the central nervous system characterized by loss of dopamine producing neurons in the substantia nigra and the presence of Lewy bodies in the substantia nigra and locus coeruleus. "Akin to aggresomes observed for Alzheimer’s and Parkinson’s diseases, where a multitude of hallmark fibrillar proteins co-aggregate, DISC1opathies, i.e., proteinopathies with aggregation or misassembly of the DISC1 protein, may feature a similar tendency for DISC1 and some of its partner proteins." (PMID 34921141, 2021).
schizoaffective disorder (4 papers, 2011 to 2020).
velocardiofacial syndrome (4 papers, 2011 to 2019). "There is a limited number of loci of relatively high impact such as Disrupted in schizophrenia 1 (DISC1), first characterized as a risk factor in a Scottish family, or the deletion 22q11.2, which causes the DiGeorge syndrome." (PMID 27690184, 2017).
viral infection (4 papers, 2011 to 2022). "In the present study, we combine the abnormally translocated DISC1 gene with viral infection causing maternal immune activation." (PMID 31733940, 2020). "Like CA10, DISC1 has ties to both pulmonary disease and viral infections." (PMID 34409086, 2021). "Four additional positional candidate genes, carbonic anhydrase 10 (CA10), CWC22 spliceosome-associated protein (CWC22), DISC1 scaffold protein (DISC1), and nitric oxide synthase 1 adaptor protein (NOS1AP), have roles in pulmonary dysfunction, viral infections, or both." (PMID 34409086, 2021).
Huntington disease (3 papers, 2011 to 2021). Huntington disease (HD) is a rare neurodegenerative disorder of the central nervous system characterized by unwanted choreatic movements, behavioral and psychiatric disturbances and dementia. "Of potentially greatest interest was the novel finding of a high degree of connectivity between the DISC1 scaffold protein, linked to psychiatric illness, and huntingtin, the protein which is mutated in Huntington's disease." (PMID 21298101, 2011). "The re-analysis of this dataset has revealed a strong network linking DISC1 and huntingtin protein, which is mutated in Huntington's disease, consistent with DISC1 and huntingtin regulating convergent pathways." (PMID 21298101, 2011). "Overall, this study demonstrates that [11C]rolipram PET is suitable to measure protein-protein interactions between DISC1 and PDE4 in vivo, that might also be interesting to be examined in further neuropsychiatric disorders in which DISC1 is dysregulated, including Huntington’s disease." (PMID 33917199, 2021).
frontotemporal dementia (2 papers, 2019 to 2020). Frontotemporal dementia (FTD) comprises a group of neurodegenerative disorders, characterized by progressive changes in behavior, executive dysfunction and language impairment, as a result of degeneration of the medial prefrontal and frontoinsular cortices. "A remarkable in vivo study recently showed that TDP-43 and DISC1 co-aggregate in frontotemporal lobar degeneration human samples and animal models, leading to disruption of dendritic local translation and aberrant behavior." (PMID 33363456, 2020). "Finally, a recent study identified Disrupted in Schizophrenia 1 (DISC1) to be critical to the translation initiation of postsynaptic proteins and could be responsible for some of the neuropsychiatric symptoms displayed by patients with frontotemporal dementia (FTD)." (PMID 31683805, 2019).
glioma (2 papers, 2016 to 2019). A benign or malignant brain and spinal cord tumor that arises from glial cells (astrocytes, oligodendrocytes, ependymal cells). "All the data proposed the hypothesis that down-expression of DISC1 reduced the glioma stem-like cell stemness." (PMID 27852062, 2016). "Thus it confirms that DISC1 -facilitates glioma developement by up-regulation of Drp1." (PMID 27852062, 2016).
influenza (2 papers, 2018 to 2025). An acute viral infection of the respiratory tract, occurring in isolated cases, in epidemics, or in pandemics; it is caused by serologically different strains of viruses (influenzaviruses) designated A, B, and C, has a 3-day incubation period, and usually lasts for 3 to 10 days. "Influenza infection also induces aggregation of the Disrupted-in-Schizophrenia 1 (DISC1) protein in animal and cellular models, highlighting the role of impaired protein clearance and misfolding in disease development." (PMID 40806558, 2025).
Lissencephaly (2 papers, 2011 to 2014). A spectrum of malformations of cortical development caused by insufficient neuronal migration that subsumes the terms agyria, pachygyria and subcortical band heterotopia. "The fact that impairment of LIS1 function results in migration defects and causes lissencephaly underlines the relevance of DISC1 and its interacting partners during brain development." (PMID 25071449, 2014).
opioid dependence (2 papers, 2019). "Supporting this notion, phenotypes of DISC1 mutation or deficiency share some characteristics with addictive behaviors, and rare variants in DISC1 were associated with opioid dependence." (PMID 30915712, 2019). "Unrelated studies of drug dependence have also demonstrated the significance of DISC1 pathway genes within the regulome as well, showing for instance, significant associations between rare variations found in DISC1 and GRIN2B and opioid dependence." (PMID 33981965, 2019).
amyloid diseases (1 paper, 2021). "This raises the very pertinent question whether, in addition to the similarities in structural architecture to amyloid diseases, DISC1 aggregation bears any semblance to other known proteinopathies." (PMID 34921141, 2021).
Auditory hallucination (1 paper, 2025). Perception of sounds without auditory stimulus. "Another gene associated with auditory hallucinations is PCM1, which encodes a protein that forms a complex with other members of the DISC1 interactome, including BBS4 and DISC1." (PMID 40943654, 2025). "We also identified a genetic association between DISC1 and auditory hallucinations, but only at the gene set level, specifically within the non-motile cilia assembly pathway." (PMID 40943654, 2025).
autoimmune disease (1 paper, 2023). A disorder resulting from loss of function or tissue destruction of an organ or multiple organs, arising from humoral or cellular immune responses of the individual to their own tissue constituents. "Altered DNA methylation of genes, such as, PON1, ADARB2, USP16, UHMK1, and DISC1, was previously reported to be related to cancer or autoimmune diseases." (PMID 37744384, 2023).
Chagas disease (1 paper, 2022). A parasitic infection caused by Trypanosoma cruzi. "All those genes are involved in biological process associated to Chagas disease: nervous system (LHX6, POU6F2, MDGA1, DISC1, PCSK9), immune system (ZMIZ, HLA-DRB1), Wnt pathway (DISC1), ion transport (KCNK15, PCSK9), striated muscles (SMYD3) or ATP metabolic process (ATP5S)." (PMID 36248819, 2022).
chondrosarcoma (1 paper, 2019). A malignant cartilaginous matrix-producing mesenchymal neoplasm arising from the bone and soft tissue. "Associations of DAXX, DRD3, and DISC1 expression with the clinicopathological characteristics of chondrosarcoma." (PMID 31850367, 2019). "Associations of DAXX, DRD3, and DISC1 expression and clinicopathological characteristics with overall survival in patients with chondrosarcoma, as determined by multivariable Cox regression." (PMID 31850367, 2019). "In this study, the expression and clinicopathological significance of the mental health–related proteins DAXX, DRD3, and DISC1 in chondrosarcoma tissue samples were examined, over an 84-months follow-up period." (PMID 31850367, 2019). "In immunohistochemical analysis, the rates of positive DAXX, DRD3, and DISC1 expression were significantly higher in chondrosarcoma than in osteochondroma tissue (P < 0.01)." (PMID 31850367, 2019). "Relationships of DAXX, DRD3, and DISC1 expression and clinicopathological characteristics to average survival in patients with chondrosarcoma." (PMID 31850367, 2019). "DAXX, DRD3, and DISC1 expression in chondrosarcoma and osteochondroma." (PMID 31850367, 2019).
COVID-19 (1 paper, 2022). A disease caused by infection with severe acute respiratory syndrome coronavirus 2. "A recent transcriptomics study of publicly available datasets demonstrated that DISC1 is downregulated by COVID-19." (PMID 35444632, 2022).
hyperlipidemia (1 paper, 2011). "We identified seven CNV regions that were associated significantly with hyperlipidemia and myocardial infarction in our patients through multistage analysis (P<0.001), at 1p21.3, 1q31.2 (CDC73), 1q42.2 (DISC1), 3p21.31 (CDCP1), 10q11.21 (RET) 12p12.3 (PIK3C2G) and 16q23.3 (CDH13), respectively." (PMID 22369086, 2011).
injury (1 paper, 2018). Damage inflicted on the body as the direct or indirect result of an external force, with or without disruption of structural continuity. "Taken together, these data show that the expression of TRIAD1 and DISC1 change after traumatic brain injury and that their interaction may affect the proliferation and differentiation of neural stem cells." (PMID 30409224, 2018).
lymph node metastasis (1 paper, 2017). "High DISC1 expression was correlated with smoking status (P=0.049), tumor size (P=0.013), pathology grade (P<0.001), grade (P=0.020), lymph node metastasis (P=0.032), and Ki-67 (P<0.001), p-GSK3β (P<0.001), β-catenin (P<0.001), and Cyclin D1 expression (P<0.001)." (PMID 29029423, 2017).
proteinopathies (1 paper, 2021). "Like aberrant species found in other proteinopathies among the neurodegenerative and prion amyloid diseases, DISC1 aggregates have been demonstrated to spread between cells in in vitro experiments, albeit without causing cell death." (PMID 34921141, 2021). "This piqued our curiosity whether the C-region of the DISC1 protein (perhaps also full-length human DISC1) may behave in ways comparable to other proteinopathies." (PMID 34921141, 2021).
renal agenesis (1 paper, 2019). Renal agenesis (RA) is a form of renal tract malformation characterized by the complete absence of development of one or both kidneys (unilateral RA or bilateral RA respectively), accompanied by absent ureter(s). "Other interesting candidate adaptive genes include HLA-DMA involved in immunity, FRAS1 associated with renal agenesis, SREBF2 related to female reproduction and DISC1 associated with response to the ultraviolet (UV) exposure." (PMID 34691999, 2019).
sarcopenia (1 paper, 2024). Progressive decline in muscle mass due to aging which results in decreased functional capacity of muscles. "In our study there was a positive association between tRF‐5003c and sarcopenia status suggesting that increased tRF‐5003c expression may contribute to the reduced expression of NOTCH, DISC1, and GLI2 and impaired muscle function." (PMID 38294260, 2024). "Sarcopenia was nominally associated (p < .05) with 12 tRNAs, 3 tRFs, and 6 piRNAs, with target genes linked to cell proliferation and differentiation such as Notch Receptor 1 (NOTCH1), DISC1 scaffold protein (DISC1), and GLI family zinc finger‐2 (GLI2)." (PMID 38294260, 2024).